INS (insulin)
Diseases named in the same sentence as INS in open-access papers (continued):
Sharing a sentence is not in itself a finding about the gene and the disease.
diabetes (continued). "Diabetes mellitus (DM) is a common condition that is characterized by the impairment of the hormone insulin, which is responsible for modulating blood glucose levels." (PMID 37761009, 2023). "Diabetes mellitus (DM) is defined as a group of metabolic diseases characterized by chronic hyperglycemia resulting from defects in insulin secretion or action." (PMID 37653931, 2023). "Next, to determine whether NLRP3 inflammasome is involved in the regulation of pre-diabetes and exercise on systemic insulin sensitivity, we performed correlation analysis between the protein levels of NLRP3 inflammasome components and the value of HOMA-IR in the whole samples." (PMID 36817440, 2023). "The absence of a measure of insulin secretion meant we were unable to study how zinc status might on diabetes risk via an effect on early phase insulin secretion." (PMID 36693633, 2023). "Additionally, higher individualised HbA1c targets may be appropriate in individuals who are older, with a longer duration of diabetes and severe established vascular complications, as is reflected in the insulin-treated cohort." (PMID 37152098, 2023). "Diabetes mellitus (DM) is a chronic metabolic condition characterized by elevated blood glucose levels due to insufficient insulin secretion and/or insulin resistance (IR)." (PMID 37441493, 2023). "The defects in insulin action and/or secretion are present in diabetes mellitus, which sums up a group of chronic metabolic diseases that imply elevated blood glucose values, mentioning that insulin action and/or secretion disorder may coexist in the same patient." (PMID 37510181, 2023). "Thus, the insufficient secretion of insulin during pregnancy tends to lead to diabetes." (PMID 36983587, 2023). "For example, eating fresh grapefruit before meals significantly reduces weight while improving insulin resistance, polyphenols in strawberry fruits improve insulin sensitivity, and carambola juice may lower the blood glucose concentration and improve liver function in mice with diabetes." (PMID 37214237, 2023). "In many people with insulin-treated diabetes, an impaired awareness of hypoglycemia may occur." (PMID 37887414, 2023). "We explored other potential pathways that might mediate the association of fitness on type 2 diabetes risk, given the observed strong link between fitness and fasting insulin levels did not wholly explain the causal association between fitness and diabetes." (PMID 37400433, 2023). "Furthermore, the diabetic condition was characterized by a lower survival at 2 years vs no diabetes regardless of the need for insulin use, but all-cause mortality in the subgroup with diabetes on insulin was higher compared with diabetes not on insulin." (PMID 35976428, 2023). "Diabetes mellitus (DM) is a metabolic disorder characterized by chronic hyperglycemia arising from inadequate insulin secretion, insulin resistance, or both." (PMID 37623290, 2023). "Importantly, some of the microalgae and bioactive compounds exhibit antioxidant, anti-inflammatory, and immune-modulatory properties, and improve insulin sensitivity that could potentially alleviate diabetes mellitus." (PMID 37755075, 2023). "The etiology of type 1 diabetes mellitus is the obstruction of insulin secretion of pancreatic cells, which leads to the unregulated high blood sugar level of the body, whereas type 2 diabetes mellitus is manifested by congenital insulin resistance or insufficient insulin secretion." (PMID 37107215, 2023). "In addition, smoking and alcohol consumption reduce diabetes control rates because nicotine exposure may induce a pro-inflammatory metabolic state, which affects insulin sensitivity and β-cell function." (PMID 37046317, 2023). "Diabetes mellitus (DM) is a group of metabolic diseases characterized by increased blood glucose due to genetic and environmental effects, resulting in defective insulin secretion and reduced sensitivity of target cells to insulin." (PMID 36820318, 2023).
diabetes (continued). "According to the World Health Organization, diabetes mellitus (DM) is defined as “a metabolic disorder of multiple etiologies characterized by chronic hyperglycemia with disturbances of carbohydrate, fat, and protein metabolism resulting from defects in insulin secretion, insulin action, or both”." (PMID 37663987, 2023). "Because diabetes mellitus involves substantial alterations in insulin levels and sensitivity and, hence, glucose levels, safety and tolerability of intermittent fasting in this condition, particularly in those receiving insulin and oral hypoglycemic agents, warrant more trials." (PMID 37043764, 2023). "Diabetes mellitus (DM) is a condition in which an individual is unable to either produce insulin, use naturally produced insulin correctly, or produce enough insulin to break down blood glucose." (PMID 37430572, 2023). "In diabetics, the risk of PAD increased with age, diabetes duration, insulin use, and the presence of peripheral neuropathy; every 1% increase in HbA1C was associated with a 26–28% increase in the risk of developing PAD, according to the UK Prospective Diabetes Study (UKPDS)." (PMID 36514151, 2022). "Regarding diabetes mellitus-related hyperglycemic conditions, it is well known that excess intracellular glucose is converted to sorbitol by the polyol pathway, mainly in tissues and organs with an insulin-independent glucose uptake (e.g., retina, peripheral nerves, kidney, erythrocytes)." (PMID 35407097, 2022). "Diabetes mellitus (DM) is a group of metabolic disorders that results from insufficient insulin secretion or inappropriate insulin signal transduction, which establishes a state of hyperglycemia." (PMID 35629342, 2022). "Insulin resistance is an early symptom of the pathogenesis of DM characterized by high levels of blood insulin and glucose, defined as prediabetes." (PMID 36590224, 2022). "However, in most instances of human diabetes, insufficient inhibition of protein breakdown by general absence of insulin is the primary cause for increased net loss of muscle protein." (PMID 35978710, 2022). "Five predictive variables for DR among patients with T2DM were selected by LASSO regression from 33 variables, including fractal dimension, arterial tortuosity, venular caliber, duration of diabetes mellitus (DM), and insulin dosage (P< 0.05)." (PMID 36479215, 2022). "Diabetes mellitus (DM) is a chronic metabolic disorder characterized by insufficient insulin production, endogenous insulin resistance, or both, resulting in hyperglycemia." (PMID 35712240, 2022). "Whether this enzyme is related to insulin metabolism or diabetes merits further experiments." (PMID 36348490, 2022). "Taken together, these data suggest that, despite its beneficial on-treatment effects on A1c and weight, the addition of exenatide to basal insulin in early T2DM did not further enhance underlying beta-cell function or the capacity to achieve diabetes remission." (PMID 36244997, 2022). "Also designated Mutant INS-gene Induced Diabetes of the Young (MIDY), MPS thus pertains to patients traditionally classified, on the basis of age at presentation, as either Permanent Neonatal Diabetes Mellitus (PNDM) or Maturity Onset Diabetes of the Young (MODY)." (PMID 35299972, 2022). "Diabetes mellitus (DM) was induced with a single intraperitoneal dosage of the glucose analogue STZ (55 mg/Kg) known to be particularly toxic to pancreatic insulin-producing beta-cells." (PMID 36431686, 2022). "The concentration of endothelin-1, among other things, increases in response to the insulin-mediated effects of increased gene expression and receptor synthesis and as a consequence of the increased presence of glycosylation products, so its vaso-active effects in diabetes are multiple and complex." (PMID 35216512, 2022). "In vitro tests and animal models of diabetes suggests that antioxidants increase insulin sensitivity and can alleviate complications brought on by insulin resistance (IR) in DM." (PMID 35600869, 2022).
diabetes (continued). "This study shows for the first time that the association of sarcopenia with low fasting insulin in the elderly is independent of whether the subjects have diabetes or not." (PMID 36482911, 2022). "Indeed, our findings in human islets are in line with previous studies revealing that increased islet Npy1r mRNA levels were present in diabetic mice induced by STZ and in aged db/db mice with full-blown diabetes featuring impaired insulin secretion due to dedifferentiated β cells." (PMID 34890851, 2022). "Given that patients with diabetes are frequently counseled on the management of their disease, health care providers such as physicians and pharmacists are uniquely positioned to lead the charge in making consumers aware of the risks of acquiring insulin from illegitimate internet pharmacies." (PMID 35156937, 2022). "It was demonstrated that early insulin secretion plays a crucial role in maintaining normal glucose homeostasis, and patients with a low insulinogenic index could be more likely to developed of diabetes." (PMID 35794584, 2022). "Diabetes mellitus (DM) is a glucose metabolism disorder characterized by chronic hyperglycemia resulting from a deficit of insulin production and/or action." (PMID 35562979, 2022). "Gliclazide (GLZ) (N-[[(hexahydrocylopenta[c]pyrrol-2(1H)-yl)amino]carbony]-4-methylbenzene sulfonamide) is a second generation sulfonylurea used for the control of type 2 diabetes mellitus (DM) by increasing insulin amount secreted by the pancreatic cells." (PMID 35706663, 2022). "The ability of IN insulin to decrease appetite and food intake in women with obesity combined with its mood enhancing effects are very promising in terms of therapeutic use of the hormone, especially given the co-morbidity of obesity, diabetes and mood disorders." (PMID 35397638, 2022). "However, when β-cells are continuously exposed to a high glucose concentration for a long period of time, the expression levels of several insulin gene transcription factors are substantially suppressed, which finally leads to pancreatic β-cell failure found in type 2 diabetes mellitus." (PMID 35453568, 2022). "This could indicate again that, unlike the anabolic treatments, the effect of insulin on bone was not a direct effect and more based on a potentially paracrine effect of the insulin-induced rescue of circulating miRNAs in synergy with the metabolic regulation of diabetes." (PMID 35742976, 2022). "It was of interest that labels that were found highly aversive by some participants (e.g., diabetes label stimulated thoughts of self-injection of insulin or exercise labels stimulated thoughts of effort required for exercise), participants could still self-exempt from these labels." (PMID 35733102, 2022). "For Model 1, five features are included in the optimal feature set of this model: family history of diabetes mellitus (DM), weight, white cell count, fasting glucose and insulin." (PMID 35064173, 2022). "Moreover, it should be noted that a complex correlation exists between zinc, insulin, and diabetes." (PMID 36291566, 2022). "Diabetes mellitus (DM) is a heterogeneous group of metabolic diseases characterised by the occurrence of chronic hyperglycaemia resulting from impaired insulin secretion or activity." (PMID 35305618, 2022). "However, the use of corrective insulin was small for patients with diabetes." (PMID 35264139, 2022). "Diabetes mellitus (DM) is a chronic metabolic disease, characterized by disturbances in insulin and glucose metabolism." (PMID 35719662, 2022). "However, the influence of factors related to diabetes (insulin, glucose, free fatty acids, cholesterol, tryptophan) that may influence the concentration of serotonin in the central nervous system requires further research and analysis." (PMID 35324747, 2022).
diabetes (continued). "Diabetes mellitus (DM) is a metabolic disorder that results in chronic hyperglycemia due to insufficient levels or impaired responses to the hormone insulin that is essential for glucose homeostasis." (PMID 35350789, 2022). "Interestingly, insulin and melatonin treatment could significantly improve myocardial tissue fibrosis and collagen accumulation caused by hyperglycemia, which illustrated that the treatment with insulin and melatonin cured diabetes-induced pathological injury." (PMID 35890121, 2022). "In light of these observations, the authors speculated that the potential effect of VitD on the risk of type 2 diabetes mellitus might be mediated through other pathways independent of insulin sensitivity and β-cell function." (PMID 36014761, 2022). "The dramatic result from the first patient in the Vertex trial, if reproduced, might come to be seen as the first clear demonstration that differentiation of stem cells into islet-like structures containing glucose-responsive insulin-secreting cells can reverse diabetes in humans." (PMID 35104802, 2022). "Dose and duration of insulin therapy, diabetes history (duration, date of diagnosis, and progression) may be misclassified; furthermore, changes in glucose-lowering medications and combined glucose-lowering medications are difficult to account, thereby possibly introducing appreciable biases." (PMID 35681699, 2022). "Hence, an agonist of FXR, such as CDCA, may be beneficial to improve insulin sensitivity and potentially be utilised in the treatment of diabetes mellitus as a therapeutic agent." (PMID 35214975, 2022). "Although alloxan produces a useful preclinical murine model of diabetes, conducting experiments in other models such as high-fat diet or streptozotocin-induced diabetes models including insulin treatment may strengthen our findings and further elucidate the potential mechanisms." (PMID 37551286, 2022). "It is possible that correlations are more significant up until the point when diabetes is severe enough to warrant insulin (ie, insulin may subsequently lower blood sugar to more optimal levels but the conditions that contributed to needing insulin may still persist)." (PMID 36222807, 2022). "The purpose of this study is to compare serum pancreatic polypeptide (PP), insulin, C‐peptide, and glucagon in different glucose tolerance stages; analyze the influencing factors of PP secretion; and further explore the role of PP in the pathogenesis of diabetes mellitus." (PMID 35437937, 2022). "Obesity is associated with metabolic diseases, including diabetes, cardiovascular disease, hyperlipidemia, and NAFLD, which are characteristics of MetS; the main consequence of a high-fat diet is the impaired action of insulin and the regulatory mechanisms of body weight." (PMID 35806234, 2022). "Previously, C-peptide was considered as a byproduct generated during insulin synthesis and only used in estimating the pancreatic function of diabetes mellitus (DM) patients." (PMID 35518934, 2022). "According to the Diabetes Complications and Control Trial (DCCT), one of the concerns in insulin-requiring diabetes is that lower average glucose and HbA1c might be achieved by increasing rates of hypoglycemia and resulting correlations with increased morbidity." (PMID 35565875, 2022). "Diabetes mellitus (DM) is a metabolic disorder characterized by chronic hyperglycemia as a result of insufficient insulin levels and/or impaired function as a result of autoimmune destruction or insulin resistance." (PMID 35203680, 2022). "However, with recent advances in translational medicine research, PDX-1 may reverse diabetes and become a valuable tool for insulin therapy strategy and an effective target of diabetes pharmacogenomics." (PMID 36551213, 2022).
diabetes (continued). "For the smallest subgroup of respondents with diabetes—those who do not use insulin or an oral medication—the association of diabetes with distal outcomes appeared to persist across all age-at-diagnosis groups, although the analyses were underpowered owing to limited sample size." (PMID 36178688, 2022). "Moreover, the insulin-loaded Pep/Gal-PNPs could increase insulin deposition in the liver and restore the liver–periphery insulin gradient in diabetes." (PMID 36333321, 2022). "Diabetes mellitus (DM) is a global public health problem that occurs when there are raised levels of glucose in a people’s blood because their pancreas either cannot produce any or enough of the hormone insulin or cannot effectively use the insulin it produces." (PMID 35797276, 2022). "In general, diabetes can be classified into the following categories: Type 1 Diabetes Mellitus (T1DM) (due to beta cell destruction, nearly always insulin deficient); Type 2 diabetes (T2DM) (due to a progressive insulin secretory defect on the background of insulin resistance)." (PMID 34991585, 2022). "In addition, they commonly present with malnutrition and chronic comorbidities with concomitant polypharmacy, such as insulin for diabetes mellitus, β agonists for pulmonary disease, and diuretics for several medical conditions, which affect the decrease in serum potassium level." (PMID 36010007, 2022). "Diabetes mellitus (DM) is a pathological hyperglycemic state related to the dysregulation of insulin." (PMID 35558755, 2022). "Shortage in insulin secretion or degradation of produced insulin is the principal characteristic of the metabolic disorder of diabetes mellitus (DM)." (PMID 35204260, 2022). "Diabetes mellitus (DM) is a chronic metabolic disease with elevated blood glucose resulted from decline in either insulin production or insulin sensitivity." (PMID 35508623, 2022). "Glucose metabolism is often impaired in diabetes mellitus (DM) due to either the inability of the pancreatic beta cells to produce insulin (type 1) or the inability of insulin to exert its effects (type 2)." (PMID 35140800, 2022). "The effects of starvation and honey on the oral glucose tolerance test, insulin tolerance test, adipocytokines, oxidative glucose metabolic enzymes, glycolytic enzymes, food intake, and body weight in rats with streptozotocin‐induced diabetes were also investigated." (PMID 36305681, 2022). "Diabetes mellitus (DM) is a disease in which the body’s ability to produce or respond to the insulin hormone is affected." (PMID 36015357, 2022). "Diabetes mellitus (DM) is a heterogeneous metabolic complaint involving increased blood glucose, which is a result of inadequate insulin secretion, diminished insulin sensitivity, or both." (PMID 36588726, 2022). "Proinsulin/insulin ratio will be analysed in archived samples from the Tanzanian cohort using a nested case-control design to investigate whether abnormal values precede diabetes." (PMID 36300035, 2022). "Decreased insulin secretion or resistance to insulin action will, therefore, affect insulin signaling in those target tissues, which may lead to impaired glucose tolerance and hyperglycemia of diabetes once β-cells are unable to compensate fully for the decreased insulin sensitivity." (PMID 36547931, 2022). "However, due to the lag in innovations in diabetes technologies, some individuals living with diabetes leveraged off-the-shelf hardware connected with custom-built software and algorithms, combined with existing on-the-market insulin pumps and CGM, arriving at an automated insulin delivery system." (PMID 35565875, 2022). "Diabetes mellitus (DM) is a collection of metabolic disorders indicated by abnormal insulin production as well as its action." (PMID 35875742, 2022). "Therefore, we supposed that thermosensitive hydrogel Poloxamer 407 combined with insulin injection might be helpful to promote wound healing for diabetes." (PMID 35311032, 2022).